PPARG (peroxisome proliferator activated receptor gamma)
Diseases named in the same sentence as PPARG in open-access papers (continued):
Sharing a sentence is not in itself a finding about the gene and the disease.
steatosis (213 papers, 2007 to 2026). Increased lipid within the cytoplasm of cells. "Research findings indicate that DLPCB causes steatosis through the up-regulation of PPARγ, which leads to an increase in lipid accumulation, and the down-regulation of PPARα, which decreases fatty acid oxidation." (PMID 38779445, 2024). "It is worth noting that the expression of hepatic genes associated with steatosis, such as peroxisome proliferator-activated receptor gamma and sterol-1c regulatory element-binding protein, is also normalized by QE." (PMID 39598636, 2024). "IRE1α-deficient mice exhibit increased steatosis and decreased plasma lipid levels due to the decreased expression of C/EBPβ, C/EBPδ, PPARγ, and triglyceride synthesis enzymes." (PMID 39125345, 2024). "Overall, our data is consistent with CYP2B6 expression leading to increased oxylipins that are associated with increased PPARγ activity and improved glucose sensitivity at the cost of increased steatosis." (PMID 36520866, 2022). "HFD administration to liver‐specific RORα‐deficient mice induced severe steatosis and obesity by dysregulating PPARγ signaling." (PMID 35412705, 2022). "Overexpression of PPARγ2 in hepatocytes increased steatosis; on the contrary, in mice hepatocyte-specific PPARγ-deficient (Pparγ-DHEP) hepatosteatosis was decreased." (PMID 34361064, 2021). "PPARα and PPARγ were also shown to be associated with steatosis and the antioxidant response, and exhibited decreased and increased protein levels, respectively, concomitant with liver damage severity in patients with WD." (PMID 34098115, 2021). "Recent studies have shown that PPARα and PPARγ are associated with steatosis and impairment of the antioxidant system in the liver of WD patients." (PMID 32485807, 2020). "Previously, we have shown that adult-onset hepatocyte-specific PPARγ knockout (PpargΔHep) mice showed reduced high-fat diet-induced steatosis associated with a reduction in hepatic CD36 expression and fatty acid uptake." (PMID 32411189, 2020). "To directly test if the increased PPARγ activity and expression are responsible for steatosis associated with Smurf1 loss, we treated a group of WT and Smurf1KO mice from the BL background with the PPARγ antagonist GW9662." (PMID 30566427, 2018). "In young BL mice (10–12 weeks of age) that had yet to develop steatosis, loss of Smurf1 increased the expression of total Pparγ (about 1.57-fold) when the mice were fed on ND, suggesting that Smurf1 has a direct causal effect on Pparγ expression." (PMID 30566427, 2018). "It is important to mention that HCV core has been shown be able to synthesize SREBP-1 but to activate PPARγ, which are suggested as mechanisms underlying steatosis development in HCV+ patients." (PMID 28218651, 2017). "Several studies attribute a causal role to PPARγ in the development of steatosis by mechanisms involving the activation of lipogenic genes and de novo lipogenesis." (PMID 22675337, 2012). "Finally, PPARG protects against MASLD, PPARG deficiency causes familial partial lipodystrophy 3 that presents with steatosis, and PPAR-γ agonists like pioglitazone are under clinical investigation for MASLD." (PMID 40065360, 2025). "Histological features were confirmed by real‐time PCR analyses, showing alcohol‐induced upregulation of the chemokines MCP‐1/CCL‐2 and CXCL1, along with the cytokine TNF‐α, implicated in hepatic inflammation, and of PPARγ that promotes both hepatic inflammation and steatosis." (PMID 39921321, 2025). "In addition, studies have demonstrated that histone H3K4 methyltransferase MLL4 is recruited to the peroxisome proliferator response elements of PPARγ and target genes in the liver, an event linked with steatosis." (PMID 35412705, 2022). "Moreover, core protein 1b can activate SREBP1 and PPARγ, which underlies the steatosis caused by HCV." (PMID 34766116, 2020).
steatosis (continued). "In addition, EGFR inhibitor-mediated reduction of hepatic PPARγ activity (mainly in hepatocytes) was associated with reduced and reversed steatosis and fibrosis in a mouse model of NASH induced with fast food diet." (PMID 32411189, 2020). "Interestingly, in a previous study it was found that Pparα and Pparγ occupied more chromatin binding sites in the livers of 21 month-old mice affecting the lipid metabolism and causing steatosis." (PMID 28068403, 2017). "Liver X receptor alpha (LXRα) and peroxisome proliferator-activated receptor gamma (PPARγ) are involved in the control of cholesterol and lipid metabolism in liver and their upregulation is associated with prominent steatosis that we demonstrated in BALB/c mice." (PMID 26218873, 2015). "PPARγ is a lipogenic transcription factor who has already been associated with steatosis." (PMID 19046413, 2008). "Moreover, in the mouse liver, TET-induced steatosis has been associated with upregulation of fatty acids elongases (Elovl 3, 5, 6) without altered expression of other genes involved in de novo lipogenesis, such as FasN, Srebp1c, and Pparγ." (PMID 24489787, 2014). "In total, we identified 27 genes, of which 3 are monogenic causes of steatosis (APOB, G6PC1, PPARG), 4 were previously associated with MASLD (APOB, APOC3, INSR, PPARG), and 23 had supporting clinical, experimental, and/or genetic evidence." (PMID 40065360, 2025). "Collectively, these results demonstrate that the ability of GA to attenuate hepatocyte steatosis is dependent on the inhibition of PPARγ signaling pathway." (PMID 40235530, 2025). "For instance, a clinical study found that the thiazolidinedione pioglitazone, a PPARγ agonist, significantly reduced steatosis contrary to what we would expect if PPARγ agonism is a steatosis MIE." (PMID 38791241, 2024). "Studies showed that increased hepatic PPARγ expression correlates with enhanced lipid storage, leading to steatosis." (PMID 39598636, 2024). "Our results showed that livers from leptin-deficient mice expressed significantly higher levels of both PPARγ (15-fold) and PPARα mRNA (>1.5-fold), suggesting that ob/ob mice exhibited increased hepatic adipogenesis and steatosis." (PMID 39201365, 2024). "Recent evidence demonstrated that FXR activation reduced PPARγ expression in the liver and induced antioxidant activity, leading to reducing liver lipid accumulation and steatosis." (PMID 39543094, 2024). "Multiple studies have shown that PPARγ regulates downstream genes, reduces the accumulation of triglycerides in cells, increases cholesterol efflux from liver tissue, and prevents steatosis." (PMID 38370081, 2024). "miR-30a-3p and miR-3666, for example, protect hepatocytes from steatosis by targeting PPARα and PPARγ, respectively." (PMID 37190114, 2023). "Multiple studies have demonstrated that the hepatic PPARγ gene serves as a promoter of steatosis by initiating the process of de novo lipogenesis." (PMID 37907845, 2023). "Increased expression of FASN, ACC, and PPARG was also observed in HepG2 cells transfected with miR-483, suggesting that miR-483 modulates the expression of steatosis/lipogenesis markers that leads to inhibition of cell steatosis." (PMID 36980601, 2023). "The upregulation of hepatic PPARγ is robustly related to fatty liver/steatosis in human and animal models." (PMID 37298094, 2023). "A significant increase in hepatic PPARγ expression is also a common phenotype in NAFLD models and is associated with increased steatosis." (PMID 36671527, 2023). "Hepatocyte-specific PPARγ activation is steatogenic: liver PPARγ overexpression increases steatosis, while liver PPARγ knockout in ob/ob mice decreases steatosis." (PMID 38039287, 2023). "In NAFLD animal and FFA-treated cell models, overexpression of lncRNA-H19 (H19) promotes steatosis and increases hepatic lipid accumulation and lipogenesis via the miR-130a/PPARγ axis." (PMID 37190114, 2023).
steatosis (continued). "Further analysis also revealed that the increased expression of USP22, PPARγ, ACC and ACLY were associated with steatosis in the HCC TMAs." (PMID 35449157, 2022). "It is known that the activation of PPARγ in the liver is connected with fat deposition in the hepatic parenchyma, whereas the activation of adipose PPARγ protects against steatosis." (PMID 35052872, 2022). "PPARγ activation in diabetic patients improves whole-body insulin sensitivity at the same time increasing steatosis." (PMID 36520866, 2022). "In vivo and in vitro experiments showed that FXR activation protects from valproic acid-induced steatosis, reducing oxidative stress and repressing the PPARγ pathway." (PMID 36430444, 2022). "Our results showed that isoorientin can reduce the oxidative damage and steatosis of hepatocytes induced by OA, with activation of the PPARγ/NF-kB p65 pathway playing a vital role." (PMID 35185572, 2022). "Praud C's results based on innovative histological techniques of fluorescence intensity measurements suggest that the balance between TGFB1 and PPARG is essential for fibrosis or steatosis induction." (PMID 35372563, 2022). "Further in-depth study of liver-specific GR-HNF4α-LXRα and GR-PPARα/PPARγ crosstalk will help understand not only fatty liver but also the progression from simple steatosis to steatohepatitis and cirrhosis." (PMID 35614477, 2022). "In contrast to PPARα, the expression of PPARγ in the liver increased as steatosis develop in rodents." (PMID 35528835, 2022). "SHP is induced in NAFLD, and SHP induction promotes steatosis but inhibits inflammation, partly via induction of PPARγ and suppression of NF-kB." (PMID 35614477, 2022). "Pioglitazone is an insulin sensitizer that acts on the peroxisome proliferator-activated receptor γ (PPARγ) to reduce steatosis by increasing lipid oxidation, thereby preventing NASH." (PMID 35958576, 2022). "Apart from rate-limiting enzymes like ACC1 and FASN, several fatty acid synthesis/lipolysis genes are regulated by peroxisome proliferator-activated receptor γ (PPARγ) in liver, and hepatocyte-specific PPARγ KO mice are protected from HFD-induced steatosis." (PMID 35428314, 2022). "Our data showed that oleic acid induce oxidative damage and steatosis in hepatocytes both in vitro and in vivo, and activate the PPARγ/NF-κB p65 signal pathway." (PMID 35185572, 2022). "Previous studies suggested that liver‐specific deletion of PPARG in mouse hepatocytes protects against development of steatosis." (PMID 34184762, 2021). "Our results suggest that the dual activation of PPARα and PPARγ by saroglitazar can effectively improve steatosis, fibrosis, and aspects of necro-inflammation in the HF-induced NASH model better than fenofibrate and pioglitazone." (PMID 34593018, 2021). "The present study will continue previous work to explore the role and possible mechanism of TWIST1, TWIST2, and PPARγ in the development of hepatocyte steatosis." (PMID 33879188, 2021). "GW9662 alleviated ethanol-stimulated hepatocyte steatosis through inhibiting PPARγ pathway, so YCHT also should exert its anti-ethanol-stimulated hepatocyte steatosis efficacy through PPARγ pathway." (PMID 35003311, 2021). "Previous study demonstrated pioglitazone (a thiazolidinedione) is a peroxisome proliferator–activated receptor γ (PPARγ) agonist that improves steatosis, inflammation, and ballooning in patients with NAFLD." (PMID 34884968, 2021). "An increase in expression of PPARγ is one of the features of the steatotic liver and it is suggested that inhibiting the activity of PPARγ would be beneficial in the prevention of steatosis and improving glucose metabolism." (PMID 33076522, 2020). "Consistent with previously published work, our data also show that (i) hepatocellular PPARγ overexpression induces hepatic steatosis." (PMID 32963510, 2020). "By contrast, C/EBPβ overexpression increases the hepatic prevalence of PPARγ, ER stress, NF-κB activation, and steatosis." (PMID 32660130, 2020).
steatosis (continued). "Conversely, PPARγ induction by rosiglitazone decreases the number of hepatic Kupffer cells, attenuating the inflammatory response as well as steatosis in a diet-induced mouse model of NAFLD." (PMID 32660130, 2020). "By contrast, hepatocyte-specific knockout of PPARγ reduces high-fat diet-induced steatosis and proinflammatory and profibrogenic events in mouse models of alcoholic liver disease." (PMID 32411189, 2020). "Overall, these data suggested that MCD diets promoted steatosis and altered the composition of fatty acids in the liver independently of hepatocyte PPARγ or CD36 expression and hepatic fatty acid uptake." (PMID 32411189, 2020). "In fatty liver, CD36, together with LXR, pregnane X receptor (PXR), and PPARγ, is involved in the regulation of free fatty acid uptake and steatosis." (PMID 31336903, 2019). "ob/ob mice with a hepatocyte-specific deletion of PPARγ are resistant to steatosis, indicating the essential role of PPARγ in the development of fatty liver." (PMID 30621686, 2019). "Hepatic PPARγ was significantly elevated in patients with NAFLD, and PPARγ deletion in murine liver cells has been demonstrated to prevent liver injury and steatosis." (PMID 31877869, 2019). "In any event, the steatosis observed in Smurf1KO mice is consistent with the heightened PPARγ activity in the liver." (PMID 30566427, 2018). "Recent studies showed that activation of PPARγ induces hepatic steatosis, and that lipid accumulation is exhibited in PPARα-deficient mice." (PMID 30298052, 2018). "Previous work also showed that PPARγ promotes metabolic adaptations downstream of the PI3K/Akt pathway that favor hepatocyte steatosis." (PMID 29183361, 2017). "Taken together, our results demonstrate that the hepatic steatosis observed in apoD Tg mice is a consequence of increased PPARγ transcriptional activity by AA leading to increased fatty acid uptake by the liver." (PMID 26083030, 2015). "Conversely, hepatic PPARγ overexpression results in exacerbated steatosis by mechanisms involving activation of lipogenic genes, thereby increasing de novo lipogenesis and hepatic triglyceride content." (PMID 24799887, 2014). "In NAFLD, PPARγ is upregulated in liver tissue and liver-specific PPARγ knockout mice are protected from diet-induced steatosis." (PMID 24864249, 2014). "In fact, treatment of obese and diabetic mice with the selective PPARγ activator thiazolidinediones has been reported to result in centrilobular steatosis in the liver, and disruption of PPARγ in ob/ob mice has been shown to be beneficial to the liver." (PMID 24086674, 2013). "In mouse models, CD36 has been established as a common target gene of LXR, PXR and PPARγ in promoting steatosis." (PMID 23874477, 2013). "In vivo studies demonstrated that hepatocytes- and macrophage-specific PPARγ knockout mice were protected against high-fat (HF) diet-induced steatosis development." (PMID 23024649, 2012). "These different results can be explained, at least in part, by differences in the level of PPARγ regulation between rats and mice, the different obesity experimental models evaluated, and the degree of steatosis." (PMID 22675337, 2012). "Increased expression of PPARγ mRNA has also been observed in human livers infected with HCV, with the highest levels in patients with HCV-associated steatosis." (PMID 22966221, 2012). "Of these, our group and others have demonstrated that PPARα and PPARγ are important regulators of postischemic liver injury that exert their effects on steatosis and inflammation, which is inherent in steatotic liver surgery." (PMID 22675337, 2012). "In the liver of HCV-infected patients, PPARγ expression was found to be highly up-regulated and to contribute to the development of HCV-associated steatosis." (PMID 23024649, 2012). "PPARγ-mediated up regulation of lipogenic genes is a relatively simple mechanism for HCV-related steatosis." (PMID 22966221, 2012).
steatosis (continued). "Expression of PPARγ in the liver was augmented in murine steatosis, and adenovirus-mediated overexpression of PPARγ in the liver provokes steatosis." (PMID 22190905, 2011). "The mechanistic relationship between steatosis and the increase of PPARγ expression in the liver is still unclear." (PMID 20981297, 2010). "The genes we identified as steatosis-associated by the network analysis, such as ACOX1, SCD, PPARγ, CFD and CIDEC were re-discovered by the regression analysis." (PMID 19680557, 2009). "Together, these studies indicate thathepatocyte PPARγ is required for basal fat tolerance and,in addition, for steatosis of the diabetic liver, which serves toimprove TG homeostasis and dampen systemic IR." (PMID 17389768, 2007). "As in muscle, basal PPARγ expression in liver is minimal.However, hepatic PPARγ expression is induced substantiallyduring steatosis." (PMID 17389768, 2007). "H19 promotes steatosis and lipid accumulation by modulating several pathways, including the miR-130a/peroxisome proliferator-activated receptor gamma (PPARγ) axis, MLX-interacting protein-like (MLXIPL) expression, and mechanistic target of rapamycin complex 1 (mTORC1) signaling." (PMID 40392981, 2025). "On the other hand, PPARγ, which is not expressed in the basal state in differentiated hepatocytes, is found in steatosis and steatosis-associated liver cancers." (PMID 41249163, 2025). "Increased hepatic PPARγ activity promotes lipid storage and contributes to steatosis." (PMID 40392981, 2025). "Furthermore, hepatic PPARγ expression augmented steatosis via up-regulating various proteins related to the uptake of lipid, TAG storage, and lipid droplets formation." (PMID 41144456, 2025). "Hepatic CD36 is mainly regulated by nuclear receptors LXR, PXR and PPARγ in promoting steatosis." (PMID 36410795, 2023). "The primary function of PPARγ is believed to be in adipose tissue, where it is known to induce adipocyte differentiation and promote triglyceride storage, hence reducing liver lipotoxicity and improving steatosis." (PMID 37190114, 2023). "Interestingly, in an in vitro cell model of steatosis, similar to the one we used in this study, Seo and colleagues recently showed that Ex-4 treatment significantly reduced the expression of both PPARγ and SREBP-1c." (PMID 35625757, 2022). "It was known that PPARγ may induce the transcription of the fat synthesis gene FAS in steatosis livers." (PMID 35990272, 2022). "We found that SZ-A inhibited CD36 and PPARγ mRNA expression and promoted PPARα mRNA expression, suggesting that SZ-A may decrease hepatic lipid accumulation and steatosis by inhibiting de novo lipogenesis and fatty acid uptake, while promoting β-oxidation." (PMID 35624769, 2022). "However, we cannot necessarily discount the presence of PPARγ in these extra-adipose tissues contributes to NAFLD outcomes beyond steatosis (e.g., inflammation)." (PMID 35928268, 2022). "PPARγ agonists are insulin-sensitizing agents; however, the overactivation of PPARγ may induce weight gain and steatosis in patients and animals." (PMID 35873595, 2022). "Moreover, isoorientin can significantly reduce oleic acid -induced oxidative damage and steatosis by regulating the PPARγ/NF-kB p65 signal pathway." (PMID 35185572, 2022). "In cell experiments, we discovered that YCHT or GW9662 (PPARγ inhibitor) could, respectively, inhibit PPARγ gene expression and steatosis in ethanol-stimulated hepatocytes." (PMID 35003311, 2021). "For instance, PPARG and HNF1A, master regulators for adipogenesis and the hepatic cell fate respectively, are among the top TRGs for the adipose and the liver tissues respectively and are found to be implicated in NAFLD and steatosis associated liver cancer." (PMID 34270548, 2021). "Therefore, increased protein expression and activation of PPARγ were responsible for OTA-induced steatosis." (PMID 34822586, 2021). "Thus, we consider the change in expression of Pparγ as an early event in the beginning of steatosis." (PMID 32001953, 2020).